ALAS2 (5'-aminolevulinate synthase 2)
Diseases named in the same sentence as ALAS2 in open-access papers (continued):
Sharing a sentence is not in itself a finding about the gene and the disease.
porphyria (6 papers, 2019 to 2021). Porphyria is a group of diseases in which substances called porphyrins build up, negatively affecting the skin or nervous system. "Three porphyria disorders can be classified as erythroid-specific, associated with loss of enzyme function in the heme biosynthetic pathway downstream of the ALAS2 step." (PMID 32499479, 2020). "Patients with porphyrias should always be assessed for the presence of the ALAS2 gain-of-function modifier variants identified here." (PMID 30678654, 2019). "The five ALAS2 single nucleotide variants had from 1.3- to 1.9-fold increases in succinyl-CoA Vmax and 2- to 3-fold increases in thermostability suggesting that most could be gain-of-function modifiers of porphyria instead of causes." (PMID 30678654, 2019). "ALAS2-overexpressing transgenic mice (Tg mice) showed syndrome of porphyria, a series of diseases related to the heme anabolism deficiency." (PMID 33785075, 2021). "The other three forms of porphyria (ADP, CEP, and EPP) are autosomal recessive conditions, although X-linked inheritance is also reported in the cases carrying GATA1 and ALAS2 mutations, which are responsible for CEP and XLP, respectively." (PMID 34441276, 2021). "This is supported by the recent siRNA knockdown of the ALAS1 mRNA showing effective prevention of adverse effects from acute hepatic porphyrias, pointing to a similar therapeutic benefit of ALAS2 inhibition for porphyrias in the erythropoietic pathway." (PMID 32499479, 2020). "In the future, we will further verify whether ALAS2-overexpressing Tg mice can be used as a porphyria model, and we will use this model to investigate the relationship of mitochondrial dysfunction and porphyria-related muscle weakness." (PMID 33785075, 2021). "ALAS2-overexpressing Tg mice were developed to investigate the mechanism of porphyria." (PMID 33785075, 2021). "All porphyrias are caused by decreased activity of one of the enzymes in the heme biosynthetic pathway, with the exception of XLP, which is a consequence of gain-of-function variants in the ALAS2 gene, leading to increased ALAS2 activity." (PMID 34679493, 2021). "The roles of ALAS2, GATA1, and CLPX genes in the pathogenesis of porphyria have been identified." (PMID 34441276, 2021). "ALAS2-overexpressing Tg mice also show accumulation of ALA, thus it may be a new model of porphyria." (PMID 33785075, 2021).
X-linked dominant protoporphyria (6 papers, 2009 to 2025). "The second type is further divided into classical erythropoietic protoporphyria (EPP) caused by ferrochelatase (FECH) loss-of-function mutation, and X-linked dominant protoporphyria (XLPP) caused by aminolavulinic acid synthetase 2 (ALAS2) gain-of-function mutation." (PMID 39965404, 2025). "In about 2% of patients, overt disease was recently shown to be caused by gain-of-function mutations in the erythroid-specific aminolevulinic acid synthase 2 (ALAS2/ALAS, EC 2.3.1.27) gene and named X-linked dominant protoporphyria." (PMID 19744342, 2009).
iron deficiency (5 papers, 2009 to 2022). "The second prevents IRPs binding to ALAS2 mRNA, thus impairing post-transcriptional inhibition under iron deficiency." (PMID 34940556, 2021). "In EPP patients with deficient FECH, iron deficiency might lead to less PPIX accumulation by inhibiting ALAS2 but should also increase PPIX level by inhibiting FECH action." (PMID 34940556, 2021). "Elevated zinc chelated-protoporphyrin levels could indicate iron deficiency or lead poisoning but also now the X-linked EPP due to ALAS2 gain of function mutations." (PMID 19744342, 2009). "Thus, it is appealing to hypothesize that the frequent iron deficiency in patients mitigates the ALAS2 overexpression via the IRE/IRP system." (PMID 34940556, 2021). "While iron deficiency leads to inhibition of the ALAS2 mRNA translation, increases in the intracellular iron levels cause degradation of the iron-responsive elements, which allows for the activation of ALAS2 mRNA translation and in turn increases synthesis of the ALAS2 enzyme." (PMID 34679493, 2021). "Consistent with their different evolutionary purposes, the two isoforms are regulated by different stimuli: ALAS1 is under a negative feedback by heme, whereas ALAS2 is repressed by iron deficiency." (PMID 36144223, 2022). "Therefore, the outcome on PPIX level might depend on the relative sensitivity of ALAS2 and FECH to iron deficiency." (PMID 34940556, 2021). "Under conditions of iron deficiency, ALAS2 translation is inhibited by the binding of IRPs to the IRE; in contrast, IRPs detach from the IRE under conditions of iron sufficiency, resulting in increased ALAS2 translation (for the IRP-IRE system, described later)." (PMID 26557657, 2015). "In CEP, it could be hypothesized that without the induction of ALAS2 expression, such as seen in FECH deficient patient, iron deficiency efficiently succeeds in inhibiting ALAS2 mRNA translation via the IRE/IRP system." (PMID 34940556, 2021).
erythropoietic porphyria (3 papers, 2019 to 2021). "The ALAS2 overexpression or gain-of-function mutations in erythropoietic porphyrias suggest that ALAS2 expression could be a target for therapeutics aiming to reduce its activity." (PMID 34940556, 2021). "Data on patients with erythropoietic porphyrias suggests that ALAS2 is one of them." (PMID 34940556, 2021). "Then, we will describe how iron availability can modulate the heme biosynthetic pathway activity, with a focus on ALAS2 and FECH regulation in patients with erythropoietic porphyrias." (PMID 34940556, 2021).
COVID-19 (2 papers, 2023 to 2025). A disease caused by infection with severe acute respiratory syndrome coronavirus 2. "The results indicated six hub DEGs for comparison of T1DM and COVID-19 convalescence (CD3G, YES1, ALAS2, MYO1C, NCR3, PRKACB) and two hub DEGs for comparison of T2DM and COVID-19 convalescence (PTRF, EHD1)." (PMID 38169604, 2023). "Also, while both IL-5 and ALAS2 were enriched in group 4, IL-5 appeared to have no significant role in COVID-19." (PMID 41839673, 2025).
hypochromic anemia (2 papers, 2006 to 2014). Anemia caused by the reduction of hemoglobin in relation to the red cell volume. "Using positional cloning strategies, it has been reported that the sau gene encodes for ALAS2, thus confirming that loss of ALAS2 leads to a microcytic, hypochromic anemia similar to XLSA." (PMID 24782769, 2014).
leukaemias (2 papers, 2010 to 2024). "We observed up-regulation of ALAS2 only in the three erythroid leukemia lines included in the panel [MEL, K562, and human erythroleukemia (HEL)] and not in cell lines derived from other lineages." (PMID 38295180, 2024). "Alas2 (Aminolevulinic acid synthase 1), involved in the heme biosynthesis, is under-expressed in the leukaemias in comparison to the control and its expression increases during erythroid differentiation." (PMID 20102610, 2010).
microcytic anemia (2 papers, 2013 to 2023). Anemia in which the red blood cell volume is decreased. "Therefore, CSA patients with microcytic anemia, in whom mutations of ALAS2 gene were not identified, were expected to harbor SLC25A38 mutation; however, it was not detectable in this study." (PMID 22983749, 2013).
Obesity (2 papers, 2012 to 2021). Accumulation of substantial excess body fat. "RT-PCR analysis showed downregulation of FOLH1, ALAS2 and LOC100855540 genes, and upregulation of BCL2L15 gene, suggesting that the metabolic difference between normal and mild to moderate obesity was involved in the hemoglobin metabolism." (PMID 34258471, 2021). "The PBMC expresses the novel components identified as essential for prevention of obesity, and those are related to the hemoglobin metabolism, such as LOC100855540 and ALAS2." (PMID 34258471, 2021). "An increase of up-regulated genes selectively expressed in erythrocytes/reticulocytes (including ALAS2 and ERAF/AHSP, and many other EDS genes) in whole blood was also noted to be consistent with previous observations of higher red blood cell counts (hematocrit) in obesity." (PMID 22545094, 2012).
Parkinson disease (2 papers, 2022). A progressive degenerative disorder of the central nervous system characterized by loss of dopamine producing neurons in the substantia nigra and the presence of Lewy bodies in the substantia nigra and locus coeruleus. "Up-regulation of α-synuclein (SNCA) can induce autosomal dominant Parkinson’s disease, and SNCA and ALAS2 are co-expressed, suggesting that ALAS2 may play an important role in the pathogenesis of Parkinson’s disease." (PMID 35204186, 2022).
acute myeloid leukemia (1 paper, 2023). Acute myeloid leukemia (AML) is a group of neoplasms arising from precursor cells committed to the myeloid cell-line differentiation. "Downregulation of ACSL5 could be an independent prognostic factor for early recurrence of colorectal cancer, meanwhile dysregulated ALAS2 expression was related to the risk of acute myeloid leukemia." (PMID 37268653, 2023).
bone marrow failure syndrome (1 paper, 2024). "Given the frequency of BM failure within the pedigree, we examined known recurrent mutations of inherited bone marrow failure syndromes, such as mutations in genes encoding ribosomal proteins (RP), ALAS2, GATA1, CDAN1, EPO, EPOR, etc.." (PMID 38971858, 2024).
cervical carcinoma (1 paper, 2014). A carcinoma arising from either the exocervical squamous epithelium or the endocervical glandular epithelium. "In order to assess the prospective utility of ALAS2 variants in PPIX production for PDT, K562 human erythroleukemia cells and HeLa human cervical carcinoma cells were transfected with expression plasmids for ALAS2 variants with greater enzymatic activity than the wild-type enzyme." (PMID 24718052, 2014).
chronic myeloid leukemia (1 paper, 2024). "We modified chronic myeloid leukemia K562 cells with CRISPR/Cas9-mediated KO of the genes encoding FECH and ALAS2." (PMID 38649187, 2024).
Hypertension (1 paper, 2012). The presence of chronic increased pressure in the systemic arterial system. "The specific overexpression of ALAS2 and ERAF in hypertension samples was confirmed by RT-PCR." (PMID 22545094, 2012).
liver disease (1 paper, 2009). "Patients who have FECH mutations on both alleles or a gain of function mutation of ALAS2 have an increased risk of liver disease though together they account for only a small proportion of those with liver disease." (PMID 19744342, 2009).
liver failure (1 paper, 2025). A liver disease characterized by the liver losing or has lost all of its function. "Studies across different cohorts have shown that 2%–10% of patients affected by PPIX accumulation carry gain of function mutations in ALAS2, and that XLEPP is associated with higher blood PPIX concentrations and an increased risk for liver failure as compared to EPP1." (PMID 40017630, 2025).
lung carcinoma (1 paper, 2014). "In an attempt to restrict photosensitivity by biological, rather than just chemical or physical means, an adenovirus expressing human ALAS2 with mutated HRMs was generated and H1299 lung carcinoma cells were successfully infected." (PMID 24718052, 2014).
myeloid leukemia (1 paper, 2024). A clonal proliferation of myeloid cells and their precursors in the bone marrow, peripheral blood, and spleen. "ALAS2 belongs to the 10% of genes that were not expressed in most of the large tumor collections, except myeloid leukemias (<2% of total tumors)." (PMID 38649187, 2024). "Consistent with these forward genetic results, the gene expression patterns in ∼10,000 patient tumors from the Genotype-Tissue Expression (GTEx) and The Cancer Genome Atlas (TCGA) datasets show that ALAS2 expression is absent in most tumors except myeloid leukemias." (PMID 38649187, 2024).
myocardial infarction (1 paper, 2025). Gross necrosis of the myocardium, as a result of interruption of the blood supply to the area, as in coronary thrombosis. "The binding of lncRNA‐SNHG8 and PTBP1, which regulates ALAS2 expression, increases oxidative stress and promotes myocardial infarction." (PMID 40032652, 2025).
non-small cell lung carcinoma (1 paper, 2020). A group of at least three distinct histological types of lung cancer, including non-small cell squamous cell carcinoma, adenocarcinoma, and large cell carcinoma. "As for ALAS gene, in non-small-cell lung cancer, non-erythrocyte ALAS1 gene transcription levels and ALAS1 protein levels were significantly elevated in cancer cells, while ALAS2 transcription levels were increased nearly 5-fold in HCC4017 cells." (PMID 33042807, 2020).
ovarian carcinoma (1 paper, 2023). A malignant neoplasm originating from the surface ovarian epithelium. "The expression of ALAS2, HMBS, and FXN involved in iron utilization was associated with improved OS in ovarian cancer, whereas the expression of ALAD, ALAS1, and CPOX in this process was associated with poor OS in ovarian cancer." (PMID 38186569, 2023). "The expression of ALAS2 and HMBS involved in iron utilization was associated with improved PFS in ovarian cancer, whereas expression of ABCB7, ALAD, FXN, UROS, ISCU, and CPOX in this process was associated with poor PFS in ovarian cancer." (PMID 38186569, 2023).
photosensitivity (1 paper, 2022). "For example, ferrochelatase deficit-accumulating free PpIX in the skin leads to photosensitivity, as well as gain of function of 5-ALA synthase 2 (ALAS2) leading to accumulation of PpIX-Zinc and photodermatosis." (PMID 36077783, 2022).
pulmonary arterial hypertension (1 paper, 2024). Pulmonary arterial hypertension (PAH) is a group of diseases characterized by mean pulmonary artery pressure >20 mmHg and elevated pulmonary arterial resistance leading to right heart failure. "The glycolysis genes (ACSS2, ALAS2, ALDH3A1, ADOC3, NT5E, and TALDO1) identified in this study play important roles in the development of pulmonary arterial hypertension, providing new evidence for the involvement of glycolysis in PAH." (PMID 38837574, 2024).
Q fever (1 paper, 2019). A bacterial infection caused by Coxiella burnetii. "When comparing QFS to asymptomatic Q fever seropositive controls, this is ALAS2 (4.4 log 2 fold change; P = 1.81 × 10−5) for the up-regulated genes." (PMID 31088495, 2019). "Another gene of interest is ALAS2, which is up-regulated in QFS patients compared to both healthy controls and asymptomatic Q fever seropositive controls, making it potentially specific for QFS." (PMID 31088495, 2019).
sarcopenia (1 paper, 2024). Progressive decline in muscle mass due to aging which results in decreased functional capacity of muscles. "The role of ALAS2 in sarcopenia warrants further investigation." (PMID 38415056, 2024). "In frailty and sarcopenia, up-DEGs including GRN2A (combined score: 0.991) and down-DEG ALAS2 (combined score: 0.991) interacted with glycine." (PMID 38415056, 2024).
Sepsis (1 paper, 2019). Sepsis is defined as life-threatening organ dysfunction caused by a dysregulated host response to infection. "We conclude that the heme and hemoglobin metabolism is modulated during sepsis, with emphasis in the four genes ALAS2, AHSP, HBD, and CA1, common to the three datasets." (PMID 31396396, 2019). "Thus, four common genes were found upregulated in the three datasets (ALAS2, AHSP, HBD and CA1), notably, they were most significantly expressed in follow-up samples of patients who survived sepsis." (PMID 31396396, 2019).
skin photosensitivity (1 paper, 2021). "Accumulation of PP-IX in this disorder results in severe skin photosensitivity, ALAS2 (step 1) gain-of-function mutations result in X-linked porphyria, which, similar to erythropoietic porphyria, is also associated with cutaneous PP-IX accumulation and skin photosensitivity." (PMID 34073678, 2021).
spinocerebellar ataxia (1 paper, 2016). "These include mutations in ALAS2 (5′-aminolevulinate synthase 2) seven-codon in X-linked SA, mutations in ABCB7 in X-linked SA with spinocerebellar ataxia, and mutations in GLRX5 (glutaredoxin 5) in congenital SA, among many others (for a recent review, see Cazzola and Malcovati 2015)." (PMID 27151974, 2016).
stem cell leukemia (1 paper, 2013). "Other erythroid-specific enhancers have also been found in the genomic regions of GATA–1, stem cell leukemia (SCL), L-type pyruvate kinase and 5-aminolevulinate synthase 2 (ALAS2) genes, which may contribute to the restricted expression of these genes in the erythroid lineage." (PMID 23985037, 2013).
Stroke (1 paper, 2023). Sudden impairment of blood flow to a part of the brain due to occlusion or rupture of an artery to the brain. "Based on the role of metabolism in stroke, we extracted seven genes related to the “porphyrin metabolism” and “glycine, serine and threonine metabolism” pathways, including ALAS2, FECH, COX10, GCAT, HMBS, PGAM2, and AOC2." (PMID 36968495, 2023).
systemic sclerosis (1 paper, 2021). A chronic disorder, possibly autoimmune, marked by excessive production of collagen which results in hardening and thickening of body tissues. "Previous gene expression studies across multiple forms of PH, including IPAH, showed significantly increased expression of ALAS2 in both systemic sclerosis-associated PAH (SSc-PAH) and IPAH32." (PMID 34876579, 2021).
cancer (8 papers, 2014 to 2026). A tumor composed of atypical neoplastic, often pleomorphic cells that invade other tissues. "Because ALAS2, especially highly stable and active variants of ALAS2, would be useful in the development of multiplex cancer treatments involving PDT, we experimented with combination PDT and drug treatments of HeLa cells." (PMID 24718052, 2014). "In contrast to cancer cells, where ALAS2 is dispensable, normal human hematopoietic stem cells depend on ALAS2 for survival." (PMID 38649187, 2024). "Similar downregulation of Alas2 was recently cited as a potential predictive marker for radiation induced hematological toxicity in cancer patients." (PMID 34364390, 2021). "ACSL5 and ALAS2 were downregulated in MCR group, they were all involved in fatty acid metabolism and played different roles in cancer." (PMID 37268653, 2023). "ALAS2 expression is not detected in any of the early human embryos, which is congruent with the non-essentiality of ALAS2 in all examined cancers." (PMID 38649187, 2024). "Finally, we discovered that the 12 IMRGs expression had significant differences, among which SFXN3, TFR2, TMPRSS6, HMOX1, and LCN2 expressions were elevated in the cancer group, and SCARA5, LTF, STEAP2, SLC39A14, CP, ALAS2, and TF were low expressed in the tumor group." (PMID 37361050, 2023). "In contrast to ALAS2, the essentiality of ALAS1 is a feature of diverse cancer cells independent of cancer type." (PMID 38649187, 2024).
tumor (6 papers, 2021 to 2024). "The erythroid lineage markers expressed in multiple tumor and tumor-associated clusters were also reflected in spatial gene expression profiles, as indicated by the high levels of Alas2, Hba-a1 and Gata1 across tumor areas." (PMID 37414763, 2023). "One tumor-associated cluster (HBB+/ALAS2+) expressed high levels of erythroid progenitor genes (KLF1) and was highly proliferative, which we annotated as tumor-associated erythroid cells." (PMID 36008377, 2022). "We found that Epcam, Gpc3 and Dlk1 were highly expressed in a small percentage of cells ( < 25%) in tumor samples compared to normal control livers although not as remarkably as the erythroid genes (Gata1, Alas2, Rhd, Hba-a1)." (PMID 37414763, 2023).